BRCA1 (BRCA1 DNA repair associated)
Diseases named in the same sentence as BRCA1 in open-access papers (continued):
Sharing a sentence is not in itself a finding about the gene and the disease.
cancer (continued). "In 2005, two landmark studies by the Ashworth and Helleday labs demonstrated that BRCA1/2-deficient cancer cells are highly sensitive to PARP inhibition." (PMID 39007266, 2024). "Specifically, statins induces SL in cancer cells with BRCA1 mutations when coupled with the inhibition of HDAC2, a histone deacetylase involved in epigenetic regulation." (PMID 39217242, 2024). "Lead, a known carcinogen, has been associated with various cancers, but its impact on BRCA1 carriers remains unexplored." (PMID 38732616, 2024). "A classic example of the use of synthetic lethality in cancer therapy is the development of poly(ADP-ribose) polymerase (PARP) inhibitors for the treatment of cancer patients carrying mutations in BRCA1/2 tumor-suppressor genes." (PMID 39007266, 2024). "The advent of poly(ADP-ribose) polymerase inhibitors (PARPi) has revolutionized the treatment landscape for cancers harboring homologous recombination (HR) deficiencies, particularly those resulting from BRCA1 and BRCA2 mutations." (PMID 38789420, 2024). "The alterations in cancer susceptible genes such as BRCA1, BRCA2, PALB2, STK11, PRSS1, and ATM have been linked to increased lifetime risks of PDAC." (PMID 38350919, 2024). "Downregulation of RNF168 protein expression sensitizes cancer cells, particularly BRCA1-deficient cells, which are resistant to DNA damage agents." (PMID 39487119, 2024). "The use of a hereditary cancer panel together with complementary immunohistochemistry for MMR detection doubled the diagnostic rate compared to BRCA1/2 testing alone and identified additional mutations and secondary findings relevant to clinical management." (PMID 39684258, 2024). "Signatures SBS2 and SBS13 are attributed to AID/APOBEC activity, while SBS3 has been associated with defective homologous recombination DNA damage repair (HR-DDR) with a strong association to somatic and germline BRCA1/2 mutations in other cancers." (PMID 39020404, 2024). "In OC, defects in the HR pathway, often due to mutations in BRCA1/2 or other HR genes, contribute to genomic instability and cancer development." (PMID 39200270, 2024). "Research in cancer biology has underscored the significance of BRCA1/2 mutations and HRD, paving the way for targeted treatments such as poly (ADP-ribose) polymerase (PARP) inhibitors." (PMID 39376601, 2024). "Individuals who carry BRCA1 or BRCA2 pathogenic variants are recommended to have extensive cancer prevention screening and risk-reducing surgeries." (PMID 37864742, 2024). "The 53BP1–RIF1–shieldin axis is pathological in BRCA1-mutated cancers, blocking homologous recombination (HR) and driving illegitimate nonhomologous end joining (NHEJ)." (PMID 39227718, 2024). "Patients carrying variants of uncertain significance expressed greater concerns about developing another cancer compared to those who had BRCA1 and BRCA2 wild type or pathogenic variants." (PMID 38500651, 2024). "Treatment with a PARPi in BRCA1 mutant cancers causes diminished heterodimerization with BRCA1 associated ring domain 1 (BARD1) and has been shown to decrease PAR formation and recruitment of BRCA1/BARD1 complex to the site of DNA damage." (PMID 38542143, 2024). "The cancers from individuals heterozygous for gPVs in BRCA1/2 were selected for having a second somatic hit rendering them BRCA1/2-deficient (available online)." (PMID 38848470, 2024). "PARP inhibitors are effective in HR-deficient cancers, particularly BRCA1/2-mutated ones, by inhibiting PARP1 and blocking DNA repair processes." (PMID 39200270, 2024). "Cancer cells bearing deficiencies in HR, such as those with mutations in BRCA1 or BRCA2 genes, tend to be vulnerable to DNA-damaging agents like platinum-based drugs." (PMID 39001539, 2024). "PARP inhibitors (PARPi), which were initially developed to treat BRCA1/2-deficient cancers by synthetic lethality, were re-purposed in clinical trials to potentiate the effects of TMZ." (PMID 39011394, 2024).
cancer (continued). "Homologous recombination deficiency (HRD) occurs in approximately half of the cancers; it is caused by germline mutations of BRCA1 or BRCA2 in at least 15%." (PMID 38175731, 2024). "There were 172 women (mean [SD] age, 47.1 [11.7] years) treated with BCT who had pathogenic BRCA variants identified using the Clinical Cancer Genetics Program Database; 92 (53.5%) had BRCA1 variants and 80 (46.5%) had BRCA2 variants." (PMID 38916888, 2024). "In another study of 13,129 cancer-free Chinese individuals, the BRCA1 and BRCA2 mutation rates were 0.2% and 0.4%, respectively." (PMID 39272924, 2024). "Recent studies suggested that RAD18 loss in BRCA1-deficient cancer cells reduces cell survival because of the role of RAD18 in ssDNA gap filling in these cells." (PMID 38943334, 2024). "Loss of BRCA1/2 and related functions in cancer is often described as “BRCAness,” which refers to both the functional defects in cancer cells and the consequent vulnerabilities." (PMID 39007266, 2024). "PARP1 inhibitors are a promising class of drug candidates that target DNA repair deficiencies in cancer cells, especially those with BRCA1/2 mutations." (PMID 39456202, 2024). "In cancers characterized by BRCA1/2 mutations, this inhibition increases the susceptibility of cancer cells to PARP inhibitors, culminating in cell death." (PMID 39555080, 2024). "In light of these findings, the therapeutic regimen was adjusted to include Olaparib, a poly (ADP-ribose) polymerase (PARP) inhibitor, specifically targeting BRCA1-mutated cancer." (PMID 39768480, 2024). "Studies on healthy and cancer cells with BRCA1/2 mutations have undoubtedly revealed the hard work for compensatory upregulation of estrogen signaling and genome stabilization via somatic mutations." (PMID 39329990, 2024). "Because BRCA1/2-deficient cancer cells are HR defective, they are forced to use error-prone repair pathways (e.g., nonhomologous end joining [NHEJ]) to repair DSBs at collapsed replication forks, leading to toxic repair products and selective killing by PARPi." (PMID 39007266, 2024). "The findings represent proof-of-concept for constitutional BRCA1 epimutations being a cancer risk factor." (PMID 40225940, 2024). "Loss of BRCA1/2 in cancer cells results in HR deficiency (HRD) and increased levels of DSBs in the genome, which likely fuels tumorigenesis." (PMID 39007266, 2024). "Based on abundant cancer-associated fibroblasts (CAFs) and frequent mutation of breast cancer-associated 1 (BRCA1) in TNBC, the characteristics of CAFs in TNBC patients with BRCA1 mutation compared to wild-type were investigated using single-cell analysis." (PMID 38182557, 2024). "SBS3, the HRD-related mutational signature, was observed to some level in 13% (2/16) of CHEK2-deficient cancers, and it was the predominant mutational signature (86%, 24/28) in the BRCA1/2-deficient group (P < .001)." (PMID 38848470, 2024). "Despite the ability of PARPi to induce synthetic lethality in BRCA-deficient cancer cells, only half of cancer patients carrying BRCA1/2 mutations respond to PARPi therapy." (PMID 39007266, 2024). "Platinum-based chemotherapy and debulking surgery are the long-standing cornerstones of therapeutic strategy, and HGSC patients have been the first to show a benefit of PARPi over other BRCA1/2-associated cancers." (PMID 38544832, 2024).
cancer (continued). "We previously reported that the expression of BRCA1 cancer-associated variants increases homologous recombination (HR) and gene reversion (GR) in yeast, confirming the potentiality of this genetic model in cancer biology." (PMID 39062754, 2024). "BRCA1 mutation genetic testing began in 1995, and since then, we have gained a lot of knowledge about cancer prevention." (PMID 38892720, 2024). "This combination of compounds does not have restrictions on the use of olaparib as a stand-alone drug, as this inhibitor has previously only been used to treat cancer patients with BRCA1 mutation and HR deficiency." (PMID 39595575, 2024). "Although BRCA1 mutations are less common in males, they still contribute significantly to the risk of pancreatic and other cancers." (PMID 39684385, 2024). "Sixth, do primary constitutional epimutations in BRCA1 (or other genes) affect the risk of diseases other than cancer?" (PMID 40225940, 2024). "To date, many miRNAs involved with the three primary missing receptors (ER, PR and HER2) of TNBC and cancer susceptibility gene BRCA1 have been identified and reported." (PMID 39744000, 2024). "Breast cancer susceptibility gene 1 (BRCA1) and breast cancer susceptibility gene 2 (BRCA2) are critical components in maintaining genomic stability through their roles in the homologous recombination (HR) pathway." (PMID 39199310, 2024). "PARP inhibitors were originally developed based on synthetic lethality in BRCA1/BRCA2-deficient cancer cells which have impairment for the double-strand break repair." (PMID 39117659, 2024). "Is it important to offer an FCR intervention that is adapted to carriers of a BRCA1/2 mutation (vs. an intervention that would include people with cancer in general)?" (PMID 38192174, 2024). "The situation with regards to the comparison of the effects of HC on cancer risk in the normal population and on BRCA1/2 pathogenic variant carriers is similar." (PMID 38892081, 2024). "Studies have shown that hypoxia-induced by anti-angiogenic therapy inhibits HR repair by suppressing the expression of key factors such as BRCA1 and BRCA2, leading to a deficiency in DDR and rendering BRCA1/2 wild-type cancer cells sensitive to PARPi." (PMID 39156700, 2024). "Based on these data, niraparib was FDA approved for patients treated with at least three chemotherapy regimens whose cancer either harbored a deleterious BRCA1/2 mutation or was platinum-sensitive with evidence of HRD." (PMID 39220639, 2024). "Mutations in BRCA1/2 genes are pivotal for DNA double-strand break repair via homologous recombination, predisposing individuals to breast and other cancers." (PMID 38910707, 2024). "PARP inhibitors are synthetic lethal with loss of HR factors and have recently been approved to treat cancers with BRCA1/2 mutations." (PMID 38286805, 2024). "Among 409 breast patients, 35 had a family history of cancer, and the proportion of BRCA1/2 mutation carriers (13/72, 18.1%) was higher than that of non-carriers (22/337, 6.5%), representing a significant difference (P = 0.002)." (PMID 38167124, 2024). "In the context of BRCA1/2-mutated cancer cells, PARP plays a pivotal role in DNA single-strand break (SSB) repair." (PMID 38139386, 2023). "BRCA1/2-deficient cancer cells depend on PARP1 for backup DNA repair leading to selective killing of these cancer cells by targeting PARP1." (PMID 37095508, 2023). "On the other hand, among patients referred for genetic testing based on family or personal cancer history, BRCA1/2 mutations are identified in up to 25%39." (PMID 37291133, 2023). "Currently, the Food and Drug Administration (FDA) has approved four PARP inhibitors (PARPi) to treat cancers with BRCA1/2 mutations." (PMID 37035242, 2023).
cancer (continued). "Conversely, ctDNA from both Patients 6 and 7 had mutations in two known cancer critical genes each (BRCA1 and IDH1, and ERG and KMT2C, respectively)." (PMID 35880692, 2023). "Polθ inhibitors are able to kill BRCA1/2-deficient cells and cancers, including BRCA1 mutant cells that are PARPi resistant through 53BP1-Shieldin loss." (PMID 38030626, 2023). "This emphasizes the involvement of the BRCA1-Akt interplay in tumorigenesis, suggesting the BRCA1-Akt pathway as a promising target in chemotherapies directed against BRCA1-deficient cancers." (PMID 36769122, 2023). "Well‐known cancer critical genes like BRCA1, IDH1, ERG, KMT2C, MSH6 and PALB2 were among the mutated genes in the metastatic samples." (PMID 35880692, 2023). "Of these, 81 cases had PVs/LPVs on BRCA1/2 (33%), 35 in other genes related to cancer susceptibility (14%), and only 3 patients had PVs/LPVs on both BRCA1/2 and other genes (1%)." (PMID 38136276, 2023). "Different types of cancer show a germline BRCA1/2 mutation (mainly ovaries, breasts, prostate, and pancreas), and a consequent high sensitivity to DNA-damaging drugs such as platinum, doxorubicin, and topoisomerase inhibitors." (PMID 38069422, 2023). "The spectrum and risk of cancer in relatives of BRCA1/2 pathogenic variant carriers in the Chinese population have not been established." (PMID 36861435, 2023). "Our findings presented here, in concert with our recently published data, indicate that BRCA1 methylation occurs as an early somatic embryonic event, affecting nearly 9% of newborn girls, and is associated with a substantial elevated cancer risk." (PMID 38053165, 2023). "Ultimately, this multifaceted approach has the potential to enhance therapeutic interventions and ameliorate the prognosis for individuals grappling with BRCA1-associated cancers." (PMID 37762577, 2023). "Further validation of Arhgap42 and Tcf12, the functions of which in cancer were previously unclear, indicated that both serve as tumor suppressor genes for Brca1-associated tumorigenesis." (PMID 37063417, 2023). "Poly (ADP-ribose) polymerase (PARP) inhibitors represent a promising new class of agents that have demonstrated efficacy in treating various cancers, particularly those that carry BRCA1/2 mutations." (PMID 37066268, 2023). "Our secondary analysis evaluated PLPV in a subset of individuals (n = 83,101) who underwent more comprehensive genetic testing beyond BRCA1/2 (ie, those who were tested for at least the 41 cancer risk genes in the group 5 genes)." (PMID 37535880, 2023). "For example, in BRCA1-mutated cancer cells, the killing effect of Olaparib treatment is observed in association with cGAS/STING pathway activation." (PMID 36706121, 2023). "In this section, we summarize and update the results of Phase III clinical trials of the four FDA-approved PARPi in treating BRCA1/2 deficient cancers." (PMID 37035242, 2023). "Although PARP inhibitors show efficacy and are well tolerated in many BRCA1/2 mutated cancers, a fraction of tumors become resistant and some patients do not respond well." (PMID 37170264, 2023). "In cancers with deficient BRCA1/2 proteins, FEN1 inhibition has been shown to increase sensitivity to DNA damage leading to cell death." (PMID 37508568, 2023). "The bias towards BRCA1/BRCA2 is in fact aligned with the higher cancer risk associated with the variants occurring in these genes." (PMID 36896237, 2023). "A higher expression of GLUT1 was observed in cancer cells that were carrying germline mutations for BRCA1." (PMID 37110218, 2023). "The human breast cancer susceptibility gene 1 (Breast Cancer susceptibility gene 1, BRCA1), which located in human chromosome 17q21, encoding a protein consisting of 1863 amino acids." (PMID 36906594, 2023).
cancer (continued). "The concept of ‘BRCAness’ refers to cancers with a defect in homologous recombination repair, mimicking BRCA1/2 loss." (PMID 37296886, 2023). "Yet, the specific effects of BRCA1/2 mutations on cancer development can vary depending on the type of mutation, its location within the gene, and other genetic and environmental factors." (PMID 37445860, 2023). "Human RRM2 is known to be implicated in cancer and has functions that range from the regulation of BRCA1 to protection against ferroptosis." (PMID 37239369, 2023). "First, some gene variants are predictive of cancer treatment efficacy; for example, BRCA1/2 for PARP inhibitors or the mismatch repair system for immune checkpoint inhibitors." (PMID 37239385, 2023). "Inhibition of Pol θ is lethal in HR-deficient cancer cells with BRCA1 and BRCA2 mutations, making Pol θ-mediated MMEJ a promising target for precision cancer therapy." (PMID 36583344, 2023). "The indirect effects on the repair of single-strand breaks and of complex single strands through poly-ADP-ribose polymerase (PARP) are successfully exploited by the use of PARP-inhibitors in different BRCA1/2-mutated cancer entities." (PMID 37623237, 2023). "PARP inhibitors were the first targeted treatments to employ synthetic lethality and were used to destroying cancers through DNA repair failure (e.g., BRCA1/2 mutation)." (PMID 36678591, 2023). "Example: Poly (ADP-ribose) polymerase inhibitors (PARPi) have shown efficacy in treating cancers with HR deficiencies, including those with mutations in the BRCA1 and BRCA2 genes, which are critical for homologous recombination (HR) repair." (PMID 37224529, 2023). "The same compounds also resulted more effective in killing BRCA1-mutated cancer cell lines (MDA-MB-436 and UWB1) thantheir WT counterparts (MDA-MB-436 + BRCAl and UWBl + BRCA1) in theCSA, demonstrating that the compounds induce SL with HR." (PMID 37134182, 2023). "For example, the G4 stabilizer CX-5461 can induce eG4 folding and stabilize eG4s in BRCA1/2-deficient cancer cells, thereby inducing replication-dependent DSBs and ultimately killing cancer cells." (PMID 37381029, 2023). "Replication-induced dsDNA breaks are faithfully repaired by homologous recombination repair (HRR) mechanism that requires BRCA1/2; therefore, cancer cells deficient in functional BRCA1 or BRCA2 are extremely sensitive to PARP inhibitors, such as olaparib." (PMID 36794257, 2023). "The multiple studies of HORMAD1 function in tumors suggest a mixture of genomic protection and disruption, depending on the stage and type of cancer or additional changes in DNA repair pathways (BRCA1/2 mutation, ATM/ATR loss, and so on)." (PMID 37838177, 2023). "Our findings reveal that haploinsufficiency in zinc finger 251, resulting in partial knockdown of ZNF251 protein (referred to as ZNF251KD), causes resistance to olaparib in multiple BRCA1-mutated cancer cell lines." (PMID 37066268, 2023). "Only sporadic ER+ cells were found at both stages, which is consistent with the current understanding that ER− luminal progenitor cells serve as the cancer cell of origin of BLBC with BRCA1 mutations." (PMID 37815460, 2023). "Just as with treatment options for these aggressive cancers, novel effective preventative therapies need to be developed for high-risk women, especially those with BRCA1/2 mutations." (PMID 37583424, 2023). "Due to the high mortality and morbidity of breast and ovarian cancers worldwide, the rapid and efficient detection of BRCA1 gene mutant variants is of great significance for predicting the risk of cancer." (PMID 37147448, 2023). "PARP-1 plays a role in DNA damage and repair, and is a well-known target for cancers with BRCA1/2 mutations." (PMID 36814851, 2023). "Presented data are relevant not only for the decision-making process of experts but also for illustration and counseling of cancer risk to healthy female BRCA1/2 carriers." (PMID 36831416, 2023).